PRL (prolactin)
Diseases named in the same sentence as PRL in open-access papers (continued):
Sharing a sentence is not in itself a finding about the gene and the disease.
tumor (continued). "DAs, especially cabergoline, are the first-choice treatment for patients with prolactin (PRL)-secreting PitNETs, since they are effective in inducing prolactin normalization and in reducing tumor size, but about 10% of patients are resistant to the treatment." (PMID 37370829, 2023). "An off-label trial of everolimus plus cabergoline in a patient with refractory prolactinoma led to significant biochemical response and regression of tumor, which stabilized for 12 months despite a subsequent rise of prolactin levels." (PMID 36968144, 2023). "Multivariate stepwise logistic regression analysis indicated that tumor size and preoperative prolactin (PRL) levels < 200 ng/ml were independent predictors for early postoperative remission in cystic prolactinomas." (PMID 37143054, 2023). "Inclusion criteria included normal prolactin level for lesions <9 mm or a prolactin level <100 ng/mL for lesions ≥10 mm in maximal tumour diameter." (PMID 37697708, 2023). "In preclinical models, mice with prolactinomas lacking the dopamine 2 receptor (D2R) exhibited higher VEGF levels, which were subsequently reduced with anti-VEGF treatment, leading to decreased tumor size, vascularity, and prolactin levels." (PMID 37529607, 2023). "In the primary DA-treated patients (n = 79), the reduction in PRL or tumor size after the first year predicted the combined response at the last follow-up (P < .001 and P = .012, respectively)." (PMID 37403202, 2023). "Among these patients, 30 had PRL PitNETs, 13 had NF PitNETs, 12 had GH PitNETs, 2 had tumors with multiple hormone secretions, and 1 patient with CD presented with tumor cystic changes." (PMID 38023185, 2023). "These treatments lead to a reduction of the frequency of headache attacks, probably due to a reduction in tumour size, normalisation of serum PRL levels, and/or blockade of nociceptor sensitization." (PMID 36967387, 2023). "Because excess prolactin is correlated with tumor size, the portion and absolute size of prolactinoma in a GH adenoma, which is correlated with the level of prolactin in blood, should also be correlated with the prognosis of testosterone level." (PMID 37886642, 2023). "Register-based study of patients with giant prolactinomas [serum prolactin (PRL) > 1000 μg/L, tumor diameter ≥40 mm] identified in the Swedish Pituitary Register 1991-2018." (PMID 37403202, 2023). "In a review of 13 studies including 97 patients with giant prolactinomas primarily treated with DA, 60% had normalized PRL levels (ranging from 17% to 100% in different studies) and 74% had a significant tumor response." (PMID 37403202, 2023). "Follow-up MRI revealed progression of tumor size, and the serum prolactin level continued to increase (730 ng/mL)." (PMID 37529607, 2023). "The tumor contained thyrotropes, somatotrophs, and lactotrophs expressing thyroid stimulating hormone, growth hormone, and prolactin, respectively." (PMID 37701167, 2023). "Most tumors in the unselected group were small and the prolactin level steadily increased with rising tumor size ( ± 23.5 mg/dL per each mm of tumor diameter, p<0.001)." (PMID 37711900, 2023). "Dopamine agonists (DA) like cabergoline typically provide sign/ symptom control, normalize prolactin levels and decrease tumor size in most patients." (PMID 37711900, 2023). "There was a weak correlation between serum PRL and maximum tumor diameter at diagnosis (Spearman ́s r = 0.35, P = .001)." (PMID 37403202, 2023). "In many patients with giant prolactinomas, DAs rapidly reduce tumor size, although with increasing tumor size the proportion of patients achieving normalized PRL decreases." (PMID 37403202, 2023). "Tumor size and preoperative PRL levels were independent factors related to remission after cystic prolactinomas resection." (PMID 37143054, 2023). "For this PitNET subtype, the tumor express Pit-1 in all tumor cells, but only the cells that express PRL also express Erα." (PMID 37762304, 2023).
tumor (continued). "A PRL-producing tumor with a level greater than 1000 ng/mL suggests a macroprolactinoma with cavernous sinus extension." (PMID 36826759, 2023). "Despite previous studies highlighting the disparity in tumor size and serum PRL levels between males and females, limited data exist regarding differences in metabolic abnormalities between the two groups." (PMID 37664314, 2023). "These tumors express Pit-1 in all tumor cells, but only the cells that express PRL also express Erα." (PMID 37762304, 2023). "This is because CAB has superior efficacy in normalizing PRL levels and reducing tumor size due to its higher affinity for D2R, leading to better cytocidal effects." (PMID 36927797, 2023). "Combining anastrozole with DA in four male patients (19–38 years) led to decreased prolactin levels and tumor shrinkage." (PMID 37958702, 2023). "DAs effectively reduced PRL and tumor size, but approximately 1 patient out of 4 needed multimodal treatment." (PMID 37403202, 2023). "The standard first-line treatment for prolactinomas are dopamine agonists (DA) such as cabergoline and bromocriptine, which have proven to be effective in reducing tumor size and controlling prolactin levels in 80-90% of patients." (PMID 37529607, 2023). "Prolactinomas in the AIPvar group, which were larger than in the unselected group, had a different secretory pattern, with the prolactin levels barely increasing by 5.8 mg/dL for each mm of tumor diameter (p=0.028)." (PMID 37711900, 2023). "Binding to the dopamine subtype 2 receptor (D2R) on lactotroph cells, DA can suppress PRL secretion, shrink tumor size and restore gonadal function effectively." (PMID 37143054, 2023). "In agreement with that, some groups have reported beneficial effects of pasireotide in resistant PRL-secreting PitNETs on both tumor shrinkage and PRL levels." (PMID 37762304, 2023). "Withdrawal of DA treatment in patients with giant prolactinomas should be an exception, and discontinuation of DA necessitates close surveillance of PRL and tumor size." (PMID 37403202, 2023). "This is consistent with our study where a weak correlation between PRL levels and baseline maximum tumor diameters was observed (r = 0.35)." (PMID 37403202, 2023). "The goals of treatment include PRL normalization and tumor size reduction with relief of the mass effect." (PMID 37143698, 2023). "This latest PitNET WHO classification also includes a new subtype of PitNET responsible for the secretion of TSH, GH and PRL: the mature plurihormonal PIT-1-lineage tumor, which is composed of monomorphous cells." (PMID 37762304, 2023). "The results from in vitro experiments have shown that the anti-VEGF-A mAb G6-31 inhibited tumor growth and decreased serum prolactin levels, especially in dopamine-agonist-resistant prolactinomas." (PMID 37958702, 2023). "In the current study, a reduction in PRL to <2×ULN or tumor size by 20% in the first year of follow-up predicted a combined response at the last follow-up." (PMID 37403202, 2023). "It is worth mentioning that, via multiplex analysis, it is not possible to differentiate between full-length PRL (23 kDa) with demonstrated pro-tumor, proangiogenic activity, and 16 kDa isoform prolactin, which was proposed as an anti-tumor marker." (PMID 37509653, 2023). "Since we previously demonstrated that 16kD prolactin requires PAI-1 to inhibit tumor angiogenesis, we investigated the possible involvement of PAI-1 in the antiangiogenic effects of 14 kDa hGH." (PMID 37240223, 2023). "Following the surgical operation and subsequent reevaluation, it was concluded the tumor was a prolactinoma and treatment with cabergoline was initiated, leading to a marked decline in prolactin levels." (PMID 36835974, 2023). "Tumour size was 28 mm at diagnosis, suggesting that the elevated serum prolactin was due to stalk compression resulting in the disinhibition of prolactin secretion from normal pituitary tissue." (PMID 37851558, 2023).
tumor (continued). "Gefitinib treatment in mice decreased ERK1/2 phosphorylation, followed by downregulation of tumor prolactin mRNA." (PMID 37958702, 2023). "Galactorrhoea was present in 12/33 patients with macro (36.4%) and in 22/41 micro (53.7%) (p = 0.138), all of which, but one (GH-secreting), were prolactin-secreting tumours." (PMID 36001286, 2023). "The Kaplan‒Meier analysis indicated that tumor size and preoperative PRL ≥ 200 ng/ml were significant predictors of followed-up remission (p = 0.025, p = 0.018, respectively)." (PMID 37143054, 2023). "Cab was shown to be superior to the first used DA Br, due to its greater efficacy in decreasing and normalizing PRL levels, reducing tumor size, and its better tolerability." (PMID 35000899, 2022). "For treating prolactinoma, dopamine agonists (DAs) are effective for decreasing PRL levels and shrinking tumor size in most patients." (PMID 35892862, 2022). "The optimal thresholds were a serum prolactin at withdrawal of ≤162 mIU/L and maximal tumor diameter at withdrawal of ≤3.1 mm." (PMID 36013562, 2022). "For the treatment of prolactinoma, dopamine agonists are effective in decreasing PRL levels and shrinking tumor size in most patients." (PMID 35892862, 2022). "It has been reported that DA treatment for giant prolactinomas results in tumor shrinkage and an improved visual field: 90% showed tumor shrinkage alone, and PRL was also normalized in approximately 75–80% of cases with cabergoline treatment." (PMID 35892862, 2022). "Our case shows a combination of features suggestive of an aggressive clinical course, including an invasive giant prolactinoma, high Ki-67 index, rising prolactin level, and recurrent tumor growth despite high-dose DA treatment and multiple surgeries." (PMID 35488355, 2022). "The inhibition of the PRLR activation by locally produced PRL showed that local PRL acts as a proapoptotic and antiproliferative factor in both primary cultures and the tumor-derived GH3 cell line." (PMID 36714572, 2022). "The pituitary MRI showed an increased tumor size (3.5 × 3.0 × 2.7 cm3) with a prolactin level of 114,235 μIU/mL." (PMID 35488355, 2022). "The aims of the treatment in these patients are the quick relief of neuro-ophthalmologic symptoms when present, the normalization of PRL levels, and tumor shrinkage." (PMID 35000899, 2022). "The overall prolactin (PRL) level at diagnosis was positively correlated with maximum tumor diameter (r = 0.469, P = 0.001)." (PMID 36337795, 2022). "Pharmacological resistance of PRL-secreting tumors is commonly defined as failure to normalize PRL levels and to achieve tumor size reduction of at least 50% upon treatment with the dopaminergic drug cabergoline." (PMID 37435454, 2022). "In some studies, untreated patients with microP during menopause had spontaneous normalization of PRL levels and disappearance of the tumor." (PMID 35000899, 2022). "In our cohort, we observed a similar trend in prolactin normalization (52.9% giant prolactinomas showed prolactin normalization) and complete resolution of the tumor was seen in only two giant prolactinomas (10.5%)." (PMID 36337795, 2022). "Regarding the findings in GBM tumor tissue, a high expression of prolactin and the prolactin receptor has been shown to have a detrimental effect on survival in males only." (PMID 35159938, 2022). "Thirteen patients underwent transsphenoidal surgery, with nine achieving full biochemical remission, two clinical improvement and near normalized prolactin levels, and one patient clinical improvement with significant tumour reduction." (PMID 35616762, 2022). "As seen in our patient, her prolactin level and tumor size responded well after she was started on cabergoline." (PMID 35488355, 2022). "The highest tumour-to-brain ratio of methionine uptake was found in prolactinomas, increasing linearly with serum prolactin level, reaching values up to 9.0 in very active prolactinomas." (PMID 35616762, 2022).
tumor (continued). "Cases of ‘selective’ resistance have been reported in a few patients in whom the drug induces discordant PRL-lowering and tumor size-reducing effects." (PMID 35000899, 2022). "In our study, immunohistochemical prolactin expression on the tumor was present in 14 out of 48 patients." (PMID 35612842, 2022). "Old series on the long-term results of external beam fractionated radiotherapy typically found tumor control in over 80% of cases and normalization of PRL levels in 20–30% of the patients." (PMID 35000899, 2022). "Cystic pituitary prolactin-secreting adenomas contain cystic parts that account for more than 50% of the total tumor volume." (PMID 35741585, 2022). "The growing recognition of the importance of tumor metabolism, and role of PRL in regulation of metabolism during lactation, points to this area for further study." (PMID 35784527, 2022). "Conversely, the regulation of the PRL secretion by CAB is mainly related to MAPK pathways as demonstrated in a rodent pituitary somatotroph tumour cell line." (PMID 35460460, 2022). "The results provide the knowledge that the overexpression of prolactin induces the disorganized amplification of the basal/stem cell compartment, which is found to be tumor-initiating cells in the prostate." (PMID 35323711, 2022). "Landolt and Osterwalder reported that patients treated with bromocriptine before surgery were significantly less likely to normalize prolactin due to perivascular and tumor fibrosis." (PMID 35807204, 2022). "Conversely, in women with evidence of macroprolactinoma and concomitant signs and symptoms of mass effects, DAs should be continued independently from PRL levels to avoid any possible tumor enlargement." (PMID 36237192, 2022). "Recently, using structure-based virtual screening, we identified a few antipsychotic drugs including penfluridol as a molecule that inhibits PRL-signaling to inhibit PDAC tumor progression." (PMID 36714582, 2022). "It has been reported that starting treatment with high Cab doses to obtain a faster PRL normalization and tumor shrinkage is the best way to obtain disease remission, but data are still scanty on this topic." (PMID 35000899, 2022). "These drugs aim to decrease prolactin (PRL) levels, reduce tumor size and normalize reproductive function." (PMID 37733390, 2022). "In our cohort, we calculated a positive correlation between prolactin level and tumor diameter (r = 0.469, P = 0.001)." (PMID 36337795, 2022). "Mixed, or plurihormonal tumors, contain GH-secreting cells that are juxtaposed with other tumor cells that stain for prolactin (PRL; i.e. mammosomatotropes), thyroid stimulating hormone (TSH), or corticotrophin (ACTH)." (PMID 35992136, 2022). "The Endocrine Society guidelines define DA resistance as failure to achieve a normal prolactin on maximally tolerated doses of a DA and failure to achieve a 50% reduction in tumor size." (PMID 36013562, 2022). "Patients in group A were significantly younger (p=0.012), had significantly higher prolactin levels at diagnosis (p<0.001) as well as smaller tumor volume (p=0.036) and lower degree of pituitary stalk deviation (p=0.009)." (PMID 36147567, 2022). "The diagnosis of prolactinomas is based on the quantitative determination of the prolactin level in the blood as well as on magnetic resonance imaging to evaluate the size of the tumor." (PMID 36540468, 2022). "The first-line treatment, dopamine receptor 2 (D2R) agonist administration, reduces PRL levels and tumor size." (PMID 36714572, 2022). "In the treatment of macroprolactinomas, cabergoline was superior to the other dopamine agonists both in terms of prolactin normalization and tumor shrinkage." (PMID 36013562, 2022). "First-line management of prolactinoma is with dopamine agonists (DA) and studies have shown that cabergoline (CAB) is more effective in lowering prolactin (PRL) levels, reducing tumor size, and has less adverse effects when compared to bromocriptine." (PMID 36337795, 2022).
tumor (continued). "A universal consensus on the definition of DA resistance is still lacking, even though the widely accepted definition is a failure to normalize PRL on maximally tolerated doses of DA and a failure to achieve at least 50% tumor size reduction." (PMID 35000899, 2022). "EPTSS for tumor resection minimizes tumor compression and reduces the PRL levels of patients, but also increases the therapeutic effect of DAs." (PMID 35741585, 2022). "DAs are not only effective in prolactin normalization and tumor shrinkage, but patients show remarkable clinical recovery as well." (PMID 36337795, 2022). "Lats1, a tumor suppressor homolog, affects the promoter activity of cellular Gh1 and Prl in pituitary tumors, and Lats1 is involved in the regulation of prolactin expression." (PMID 36555554, 2022). "Temozolomide treatment was initiated and continued for 12 cycles resulting in a normalization of PRL levels and a slight tumor volume decrease." (PMID 36157469, 2022). "Cabergoline is superior to bromocriptine in prolactin normalization and tumor shrinkage but still bromocriptine is being used in a significant number of patients in low-income countries as first-line due to its low cost." (PMID 36337795, 2022). "In patients whose PRL levels and tumor size are progressively reduced on DA treatment, the efficacy of treatment can be maintained even when DA dose is tapered." (PMID 35000899, 2022). "The prolactin level at diagnosis was positively correlated with maximum tumor diameter (r = 0.469, P = 0.001)." (PMID 36337795, 2022). "Conversely, Cab (median dose of 2 mg/week) has been found to be effective in normalizing PRL in most treated patients (74–87%), tumor shrinkage being observed in up to 80% of cases." (PMID 35000899, 2022). "At the final follow-up, PRL levels were normal in three patients, and tumor signals with cystic lesions were visible on MRI in two patients." (PMID 35741585, 2022). "Improvements in visual fields generally parallel the changes observed at imaging, whereas reductions in PRL levels usually forerun any tumor shrinkage." (PMID 35000899, 2022). "Mean age at diagnosis was 46 years (range 3–74 years); 32% of the tumours were prolactin (PRL)-secreting, 30% adrenocorticotrophic hormone (ACTH)-secreting, and 27% clinically non-functioning (NF)." (PMID 36018781, 2022). "In one review article, summarizing 12 published series of patients with macroprolactinomas (n=309) treated with CAB, prolactin normalized in 80% of the cases and the tumor shrunk significantly in 87% of patients." (PMID 36337795, 2022). "As disease progresses with dysregulation of multiple pathways, intrinsic tumor cell properties and the stromal environment are likely to alter the responses of target cells to PRL and its interactions with other potential oncogenic factors." (PMID 35784527, 2022). "The level of overproduction of prolactin usually depends on the tumor size ranging from below 200 ng/ml for tumors with a diameter less than 1 cm, 200 ng/ml to 1000 ng/ml in tumors 1 to 2 cm, and more than 1000 ng/ml in tumors sized more than 2 cm30." (PMID 36581642, 2022). "After a treatment duration of 15–56 months, serum prolactin fell by 44–97.4%, and there was a volumetric tumor reduction of between 24.5–68.7% compared to the best results achieved with cabergoline alone." (PMID 36013562, 2022). "In a murine model of HER2+ cancer (MMTV-neu), the PRL antagonist, G129R-hPRL, reduced metastases after removal of the primary tumor." (PMID 35784527, 2022). "While the initial in vitro studies showed minimal prolactin inhibition using pasireotide, there have been case reports of impressive responses both in terms of prolactin level and tumor shrinkage." (PMID 36013562, 2022). "Preclinical data, epidemiological studies, and patient tumor tissues analyses strongly support the contribution of PRL/PRLR to breast tumorigenesis and cancer progression." (PMID 36187116, 2022).